IFNG (interferon gamma)
Diseases named in the same sentence as IFNG in open-access papers (continued):
Sharing a sentence is not in itself a finding about the gene and the disease.
tumor (continued). "In summary, these results further support the hypothesis that IFNγ signaling can promote RMC tumor cell state changes, prompting further investigation into the pharmacological inhibition of myeloid-affiliated mediator, p300, which is downstream of IFNGR1." (PMID 41290625, 2025). "This activation leads to interferon‐gamma (IFN‐γ) production and consequent tumor surveillance." (PMID 39573933, 2025). "On the level of Th1, it stimulates cytotoxic activity and secretion of interferon-gamma to improve anti-tumor effects, while Tregs may diminish immune response and form an immunosuppressive environment within the tumor." (PMID 41211067, 2025). "The RNAseq results provided additional support of the CD8 and granzyme B IHC data and suggested that Th1 response might be enhanced in the post-treatment tumor microenvironment due to up-regulation of IFNg and TBX21 gene expression." (PMID 39965362, 2025). "Tumor-secreted cytokines, IFNγ and TNFα, drive cardiac repair and suppress fibrosis." (PMID 41322654, 2025). "Collectively, these findings highlight IFNG as both a key prognostic biomarker and a functional orchestrator of intercellular immune communication within the ccRCC tumour microenvironment, particularly by coordinating crosstalk between innate and adaptive immune components." (PMID 41357186, 2025). "Further investigation indicated that CD163+ PD‐L1+ macrophages primarily located in adjacent liver tissue impaired MAIT cell function through direct contact and PD‐L1‐dependent mechanisms, leading to reduced interferon‐gamma (IFN‐γ) production at the tumour‐to‐liver interface." (PMID 39924620, 2025). "For example, stimulation of macrophages in vitro with LPS ± IFNg to derive an inflammatory, anti-tumor M1 phenotype results in induction of glycolysis, whereas stimulation with IL-4 to generate an immunosuppressive, pro-tumorigenic M2 phenotype induces an increase in oxidative phosphorylation." (PMID 41044469, 2025). "However, tumor cells respond to increased levels of IFNγ in the microenvironment by upregulating immunosuppressive genes." (PMID 40035950, 2025). "Our study validated IFNG's expression and protein levels in tumor cells." (PMID 39945555, 2025). "Finally, in terms of functional activity, the reduction in degranulation capacity and IFNγ production in STS patients suggests a compromised anti-tumor immune response." (PMID 40805205, 2025). "Treatment with anti‐CD3/CD28 increased the frequency of CD137+/CD8+ T cells and induced cytokine responses dominated by IFNγ, IL‐2, and Granzyme B. While both non‐tumor and tumor‐border tissue responded to anti‐CD3/CD28, the intensities of immune responses were highly varied." (PMID 40952312, 2025). "Additionally, research has indicated that the intensity of IFNγ signaling within tumor cells is positively correlated with their responsiveness to PD-1 inhibitors." (PMID 40936907, 2025). "Notably, treatment with Nivolumab induced an inflammatory response primarily in the tumor‐border evidenced by IFNγ, IL‐2, and Perforin secretion alongside increased expression of CD107a on CD8+ T cells, in a donor‐dependent manner." (PMID 40952312, 2025). "In this context, our study strongly suggests that IFNγ likely plays a significant role in stabilising antigen presentation by myeloid subsets, especially during early tumourigenesis, which in turn modulates long-term tumour-specific T cell persistence." (PMID 39746898, 2025). "Furthermore, another interesting study analyzed the opposing effects of on interferon gamma (IFN-γ) on promoting or suppressing anti-tumor immunity depending upon the duration of IFN-γ stimulation." (PMID 40586874, 2025). "Additionally, when co-cultured with tumor cells, BBζ-Neo exhibited higher levels of IFNγ, IL-1β, IL-6, MCP-1, TNF-α and IL-8 compared to BBζ." (PMID 40025022, 2025).
tumor (continued). "CD8+ CTLs and NK cells kill cancer cells via “immunological synapses”, structured connections enabling targeted release of cytotoxic molecules (GZMB, PRF1), expression of death receptor ligands (Fas ligand FASLG), and release of tumor - directed cytokines (especially IFNγ)." (PMID 40661781, 2025). "Using the interaction of 1G4 CTL with Mel624 spheroids, the ability of SIL to kill tumor target cells and secrete IFNg was equally suppressed whether 2μg/ml exogenous NY-ESO-1 peptide was present in the spheroids or not." (PMID 40589546, 2025). "Interestingly, previous studies have shown that hypoxia in the tumor microenvironment can drive epigenetic dysregulation, impair immune cell cytotoxicity, and reduce interferon-gamma signaling." (PMID 41463204, 2025). "In HNSCC, IFNG, as a key cytokine with antiviral, immunomodulatory, and antitumor properties, primarily functions to enhance the immune response against tumor cells by strengthening antigen presentation and promoting T-cell activation, and serves as a prognostic biomarker." (PMID 41368643, 2025). "IFNγR deletion in tumours led to an increase in IFNγ signalling primarily in the myeloid compartment, suggesting that IFNγ was important for the remodelling of the myeloid compartment in IFNγRKO tumours." (PMID 39746898, 2025). "Reduced TAM levels and enhanced CD8+ T-cell-mediated tumor control and IFNγ production." (PMID 40918451, 2025). "Both IFNγ and TNFα are important inflammatory mediators in the tumor microenvironment." (PMID 39896512, 2025). "Natural killer (NK) cells play an important role in the innate immune system, with functions to directly recognize and eliminate virus-infected and tumor cells, and regulate interconnected immune responses through the secretion of cytokines such as interferon-gamma (IFN-γ)." (PMID 40872521, 2025). "IFNγ is an important cytokine that mediates the cytotoxic activity of T cells against cancer cells and promotes the recruitment of additional immune cells to the tumour site, further amplifying the immune response." (PMID 39193804, 2025). "This could potentially be achieved through therapies that stimulate M1 polarization, such as IFNγ or specific cytokine modulators, while simultaneously inhibiting M2 macrophage activity, which tends to promote tumor growth." (PMID 40330466, 2025). "We previously identified that IFNγ could sensitize tumor cells to ferroptosis by down-regulating the expression of SLC7A11." (PMID 40645933, 2025). "In addition, some cytokines in the tumor microenvironment such as interleukin-2 (IL-2), interferon-α (interferon-α, IFNα) and interferon-γ (interferon-γ, IFNγ) have also been used in immunotherapy approaches." (PMID 40672947, 2025). "As such, these observations imply that activity of these therapeutics could be enhanced by concurrent IL12 stimulation of IFNγ production immune effectors in the local tumor environment." (PMID 40560386, 2025). "In addition, both WT and IFNγRKO tumours were no longer controlled when engrafted in IFNγKO mice, demonstrating that IFNγ plays an equally important role for both tumour microenvironments." (PMID 39746898, 2025). "In addition, co-culturing PBMCs with tumor cells treated with BET/JQ1 combined with C-170 significantly boosted the production of IFNγ." (PMID 40552293, 2025). "These cells play a crucial role in tumor immunotherapy by exerting direct cytotoxicity through the production of inflammatory cytokines (e.g., interferon-gamma (IFN-γ), tumor necrosis factor-alpha (TNF-α), and interleukin-17 (IL-17)) and cytotoxic molecules (e.g., perforin and granzyme)." (PMID 40226616, 2025). "The mechanism of action of IFNγ may involve direct IFNγ‐induced apoptosis of cancer cells or stimulation of Fas expression on tumor cells." (PMID 40178291, 2025). "Additionally, genetic alterations influence tumor sensitivity to ICI, such as mutations in interferon-gamma pathway genes, which potentially limit its effectiveness despite elevated PD-L1 levels." (PMID 40361336, 2025).
tumor (continued). "Collectively, purified recombinant IFNγ and TNFα could fully recapitulate the effects of tumor-bearing serum." (PMID 41322654, 2025). "In addition, these authors showed that the paraneoplastic tissues of HTPTC patients produced more interferon-alpha (IFN-α) and interferon-gamma (IFN-γ) than tumour tissues." (PMID 40563614, 2025). "This is consistent with human data suggesting that mutations in the IFNγ pathway do not confer any advantage in tumour growth as a whole or survival, but these mutations can rise and take over other clones." (PMID 39746898, 2025). "We found that IFNγ production by CD8+ T cells mostly occurred around blood vessels in tumours." (PMID 39746898, 2025). "Immunotherapy‐activated CD8+ T cells enhance tumor radiosensitivity by IFNγ‐driven LPO." (PMID 40919133, 2025). "In conclusion, our findings indicate that bystander killing in the context of CD3xHER2 bsAbs involves initial bsAb‐mediated T‐cell cytotoxicity against HER2+ tumor areas and subsequent paracrine killing of HER2− tumor areas through IFNγ and TNFα production by the activated T‐cells." (PMID 40178291, 2025). "IFNγ also enhances HLA‐I expression to facilitate neoantigen presentation in tumor cells." (PMID 39258533, 2025). "Moreover, the tumor’s consumption of glucose can limit its availability to T cells, reducing mTOR signaling, IFNγ production, and the glycolytic capacity of T cells, further dampening their anti-tumor activity." (PMID 41019045, 2025). "Thus, in many cancers, T. gondii infection can modulate host immunosuppression to restrain tumor growth by upregulating the expression of interleukin-12 (IL-12) and interferon gamma (IFN-γ)." (PMID 40149641, 2025). "It plays a key role in shaping a favorable tumor microenvironment by promoting the differentiation of conventional T cells into effector memory T cells, which are critical for the production of the antitumor cytokine interferon-gamma (IFN-γ)." (PMID 40805165, 2025). "Within the tumor mass, L. reuteri released indole-3-aldehyde (I3A), a dietary tryptophan catabolite, which promoted interferon gamma (IFN-γ) production through activation of the AhR within CD8+ T cells, thus, enhancing anti-tumoral immunity and boosting anti-PD-L1 efficacy." (PMID 40437288, 2025). "Additionally, inhibition of FAPα promotes the activation of T-lymphocytes and NK-cells, leading to increased production of key cytokines such as IL-2 and interferon-gamma (IFNγ), which strengthen the immune response against the tumor." (PMID 40918451, 2025). "Indeed, TOX-expressing CD8+ TILs from E0771 tumours grown in DR-fed mice exhibited increased IFNγ production and elevated TCF1 levels, a marker of cell stemness." (PMID 41366157, 2025). "However, there was a notable increase in the proportion of IFNγ positive T cells in blood as well as in tumor biopsies." (PMID 40386779, 2025). "For example, CD4 + T cell-derived EVs enriched with pro-inflammatory cytokines such as IFNγ, TNFα and IL-2, are taken up by macrophages to sustain M1 anti-tumor phenotype and to stimulate cGAS-independent STING activation, subsequently inhibiting CRC progression." (PMID 40908470, 2025). "In particular, the patients showed an increase in IFNγ production by NK cells and cytotoxic T lymphocytes, and a reduction in regulatory T lymphocytes, indicating an effective proinflammatory response against the tumor." (PMID 41002413, 2025). "For instance, research has shown that T cell-derived interferon-gamma (IFNγ), when combined with arachidonic acid (AA), prompts ferroptosis in tumor cells by upregulating ACSL4 and altering lipid compositions, thereby sensitizing them to iron-dependent cell death." (PMID 39150660, 2025).
tumor (continued). "For example, an immunogenic tumor antigen may only be processed and presented when the components of the immune proteasome are upregulated in the presence of IFNγ." (PMID 41008910, 2025). "Among the factors that induce PD-L1 in the tumor microenvironment after radiation, the most potent may be IFNγ released by activated TILs themselves." (PMID 39941761, 2025). "In addition, adverse reactions induced by sustained tumor proliferation in the liver, including ascites generation, were totally suppressed by the combination of Nano-IFNγ/Zole and aPD-L1." (PMID 39776793, 2025). "In a murine transplantable tumor model, the removal of TCPTP from tumor cells led to the amplification of IFNγ-mediated effects on antigen presentation and growth inhibition, thus improving the sensitivity of cancer cells to immunotherapy and blocking cancer progression." (PMID 41302504, 2025). "Increase in tumour-specific CD8+ T cells suggests that inhibition of IFNγ signalling in tumours might alter the cytokine environment, inducing global changes in signalling pathways of other immune subsets which we explored using genomic methods." (PMID 39746898, 2025). "Notably, the combination of Nano-IFNγ /Zole with the aPD-L1 most significantly inhibited tumor growth and prolonged overall survival in tumor-bearing mice." (PMID 39776793, 2025). "Considering that Nano-Zole exhibited the strongest immune-activation and tumor-inhibition effects in different bisphosphonate-mineralized nanoparticles, subsequent studies were performed using a zoledronate-mineralized nano-IFNγ gel system to reshape TAMs after iRFA treatment." (PMID 39776793, 2025). "Around day 21 post-tumor inoculation, the tumor volume in the combination treatment group was reduced by approximately 60% compared to the control group, whereas the IFNγ monotherapy group showed only about a 30% reduction, clearly demonstrating the synergistic effect of the combination therapy." (PMID 41488647, 2025). "Notably, RGS1, CBLB, and FYN were expressed at higher levels, while IFNG was expressed at lower levels across all tumor-infiltrating NK clusters compared to the preinfusion NK clusters." (PMID 40315330, 2025). "Losing sensitivity to IFNγ may contribute to tumor immune escape, but containment of IFNγ-insensitive tumors is also reported." (PMID 39746898, 2025). "Additionally, Ccn1‐KO tumors demonstrated significantly higher protein levels of TNFα, IL2, and IFNγ in tumor and serum." (PMID 40287974, 2025). "Furthermore, MYXV followed by cisplatin potentiated splenocyte activation and IFNγ expression, likely by T cells, when splenocytes from treated mice were stimulated with tumor cell antigen ex vivo." (PMID 40005517, 2025). "Flow cytometry analysis on re-stimulated splenocytes, showed that mice treated with CBL0137 had significantly higher numbers of tumor-specific T cells, as shown by the higher percentages of T cells expressing IL-2, IFNγ or TNFα, particularly in the CD4+ T cell compartment." (PMID 39706891, 2025). "In addition, both CD4+ and CD8+ T cells from arginine- or citrulline-fed mice displayed enhanced function shown by an increase in IFNγ production in the tumor, with the biggest increase found in citrulline-treated groups." (PMID 40742298, 2025). "Finally, 21a was further proven to inhibit tumor growth, enhance gene expression levels of immune markers such as IFNγ and improve intratumoral CD8+ T cell invasion in vivo." (PMID 41032705, 2025). "Gene set enrichment analysis (GSEA) further showed hallmarks of anti-tumor immune responses being upregulated in the mDKN01-treated tumors compared to IgG, including interferon-gamma response, interferon-alpha response, TNFα signaling via NFκB, and IL-2/STAT5 signaling." (PMID 39885132, 2025). "IFNγ in turn induces release of chemokines, which recruit more T cells to the tumor." (PMID 40239619, 2025).
tumor (continued). "mRNA expression of CXCL9, iNOS, and IL-12β, anti-tumor macrophage markers, was elevated, while mRNA expression of IFNγ, TNFα, ARG-1, TGFβ, IL-10, and VEGFa, pro-tumor macrophage markers, was significantly lower in TAMs isolated from the prostates of RON∆Epi/TRAMP+ compared to RONF/F/TRAMP+ mice." (PMID 40282397, 2025). "Together, these results indicated that IFNγ is essential for the pruning of CD45−CD31high tumor endothelial cells and the accumulation of CD8+ T cells into tumors during anti-CTLA-4 therapy but not for the formation of TA-HEVs or the modulation of their phenotype." (PMID 40460830, 2025). "The increase of MHCII expression was likely a result of the increased interferon responses in tumor cells, which was partially attributed to the increased IFNγ produced by M002-activated CD4+ T cells, according to our in vitro culture and in vivo adoptive transfer assays." (PMID 39885128, 2025). "Tumor-bearing mice were treated with iRFA and Nano-IFNγ/Zole gel system." (PMID 39776793, 2025). "In contrast, multiple immune-related pathways, including interferon gamma response and inflammatory response, were significantly downregulated in CC tumors compared to AA, indicating a reduction in immune activation within the tumor microenvironment." (PMID 40565184, 2025). "In order to eliminate the negative effects of TAMs due to its contribution to residual tumor recurrence and metastasis, we designed and prepared bisphosphonate-mineralized nano-IFNγ and administered it in a single dose via intratumoral injection during RFA surgery." (PMID 39776793, 2025). "More importantly, the addition of aPD-L1 further enhanced the remodeling effect of Nano-IFNγ/Zole on the distant tumor immune microenvironment, and showed the strongest therapeutic efficacy against both primary and distant tumors with minimal influence on mice body weight." (PMID 39776793, 2025). "The inhibitory effect of IFNG on tumor angiogenesis has been widely reported." (PMID 39945555, 2025). "Additionally, PCIF1 regulates the TGF-β and interferon-gamma (IFN-γ) signaling pathways through m6Am-dependent mechanisms, thereby influencing the tumor microenvironment and response to immunotherapy." (PMID 41446042, 2025). "Some studies suggest Th1 cells may prevent tumor progression and induce cell death by activating anti‐tumor cytotoxic and NK cells via IFNγ and IL‐12 in the TME." (PMID 39817507, 2025). "Different phenotypes of tumor cells exhibit varying sensitivities to PD-1 inhibitors, which may be related to the strength of IFNγ signaling." (PMID 40936907, 2025). "As DOCK2 primarily functions as an immune modulator we examined whether immune cell dysregulation might be responsible for the observed IFNγ stimulation and thus impacting tumour formation in Dock2 deleted mice." (PMID 39242821, 2024). "However, IFNG’s role appeared context-dependent, as IFNG, being a tumor-suppressing gene, promotes tumor progression as observed in the results." (PMID 38638111, 2024). "In the TME, altering Treg function by inducing Treg fragility, with lower expression of FOXP3, enhanced production of tumor-killing cytokines such as interferon-gamma (IFNγ), could contribute to the anti-tumor therapy." (PMID 38167862, 2024). "Similarly, tumor volume was negatively correlated with IFNγ, corroborating with data in the right-sided CRC tissues from patients colonized by CoPEC." (PMID 38417029, 2024). "Furthermore, compared with ISO-PLGA-ADR nanoparticles, the treatment with TNFR2-PLGA-ADR nanoparticles markedly increased the IFNγ-expressing CD8 cells in the tumor." (PMID 39247806, 2024). "Furthermore, the cytotoxic function of CD8+T cells was enhanced in Mn‐N/C‐treated tumors, as evidenced by elevated production of cytotoxic molecules IFNγ and Granzyme B in the tumor‐infiltrating CD8+T cells after Mn‐N/C treatment." (PMID 38308189, 2024).